NUSAP1 (nucleolar and spindle associated protein 1)
Diseases named in the same sentence as NUSAP1 in open-access papers (continued):
Sharing a sentence is not in itself a finding about the gene and the disease.
urothelial carcinoma of the bladder (1 paper, 2022). "Uni- and multi-factorial Cox regression methods were used to determine the prognostic value of NUSAP1 expression in urothelial carcinoma of the bladder." (PMID 35487972, 2022). "Therefore, we examined the NUSAP1 expression and its value for prognostic assessment in urothelial carcinoma of the bladder." (PMID 35487972, 2022).
tumor (62 papers, 2004 to 2025). "Research has shown that the expression of NUSAP1 is significantly increased across various types of tumors and is closely associated with tumor invasion, disease advancement, poor prognosis, and treatment outcomes." (PMID 40535133, 2025). "Subsequent studies have revealed that NUSAP1 is associated with tumor cell proliferation and metastasis." (PMID 40393971, 2025). "Studies have shown that elevated NUSAP1 expression is closely linked to heightened tumor cell proliferation, migration, and invasion, which is associated with a poor prognosis in various solid tumors, such as breast, prostate, and lung cancers." (PMID 39975552, 2025). "Given the well-documented dysregulation of mitosis in various tumor types, the association between NUSAP1 and malignant tumor has been increasingly revealed." (PMID 39430250, 2024). "Genome heterogeneity analysis revealed that NUSAP1 is related to tumor mutation burden (TMB), loss of heterozygosity (LOH) and homologous recombination deficiency (HRD) in PDAC." (PMID 38229038, 2024). "NUSAP1 was positively related to tumor mutation burden (TMB) (R = 0.3575, P < 0.0001), loss of heterozygosity (LOH) (R = 0.1954, P = 0.0139) and homologous recombination deficiency (HRD) (R = 0.4138, P < 0.0001) in PDAC." (PMID 38229038, 2024). "Expression of NUSAP1 in tumor cells has been linked to chemoresistance, induction of tumorigenesis, cell proliferation, migration, invasion, metastasis, and even lipid accumulation." (PMID 36982952, 2023). "Increased expression of NUSAP1 is closely associated with tumor development and has been reported in prostate cancer, breast cancer, oral squamous cell carcinoma, and cervical cancer." (PMID 35487972, 2022). "To investigate the association between NUSAP1 and the tumor microenvironment, we first calculated stromalScore, immuneScore, and tumor purity in PTC tissues using the ESTIMATE method." (PMID 35710427, 2022). "By analyzing two results, we once again proved that NUSAP1 promoted tumor progression by regulating cell cycle and it was associated with G1/S phase transition." (PMID 34354737, 2021). "The genes CCNA2, CKAP2L, NCAPG, and NUSAP1 were not only significantly up-regulated in PCa tissues, but also positively associated with higher Gleason score and tumor stage, implicating significant contributions to the pathogenesis of PCa." (PMID 33927744, 2021). "Overexpression and knockdown of NUSAP1 produced changes in gene expression programs associated with tumor progression, and these gene sets predict patient outcomes in patients undergoing surgery for localized prostate cancer." (PMID 28404898, 2017). "Additional work will be necessary to understand the mechanisms underlying NUSAP1's effects on gene expression and tumor progression." (PMID 28404898, 2017). "In training set, tumor size > 5 cm, positive lymph node status, grade 3 status, and positive NuSAP1 expression were associated with a greater risk of recurrence and a lower DFS (P = 0.016)." (PMID 26485712, 2015). "Tumor size > 5 cm, positive lymph node status, and positive NuSAP1 expression were significantly associated with worse DFS (P < 0.05)." (PMID 26485712, 2015). "However, its function in cancers is context-dependent, and emerging evidence indicates that NUSAP1 possesses tumor suppressor functions, although the underlying mechanisms remain uncharted." (PMID 41178464, 2025). "Nucleosome- and spindle-associated protein 1 (NUSAP1) has recently gained attention as a key player in cancer biology, with growing evidence supporting its role in cell cycle regulation, chromosomal instability, and tumor proliferation." (PMID 39975552, 2025). "Furthermore, in mouse xenograft experiments, mutation of the R422 site abolished NUSAP1’s ability to promote tumor growth." (PMID 40393971, 2025). "Our hypothesis is that this may be linked to the reported biological function of NUSAP1 in enhancing tumor stemness." (PMID 38441732, 2024).
tumor (continued). "Finally, we also found that NUSAP1 was significantly up-regulated at transcriptional and protein levels, and associated with poor survival and advanced tumor stage among HCC patients." (PMID 35431924, 2022). "To understand the underlying mechanism, we examined whether NUSAP1 could alter the extracellular matrix around the tumor cells." (PMID 28899410, 2017). "Moreover, the statistical analysis indicated that upregulated NUSAP1 protein was associated with WHO tumor grade (P < 0.001) and vital status (P < 0.001)." (PMID 28899410, 2017). "Patients with lower NUSAP1 expression levels demonstrate extended overall survival (OS), reduced tumor proliferation, and a more favorable clinical prognosis." (PMID 40535133, 2025). "In our study, utilizing the CellMiner database, we discovered that amonafide and KPT-9274 show increased effectiveness in anti-tumor therapy for patients exhibiting low NUSAP1 expression." (PMID 39781524, 2025). "Our analysis revealed a significant upregulation of NUSAP1 in tumor tissues, with a remarkable capacity to distinguish between tumor and normal samples, boasting an area under the curve (AUC) value exceeding 0.930." (PMID 39781524, 2025). "This suggests that NUSAP1 can reflect tumor occurrence from multiple perspectives and is highly valuable for early tumor identification." (PMID 40535133, 2025). "A study utilized RT-qPCR and western blotting techniques to examine the expression levels of NUSAP1 in 47 paired tumor and adjacent non-tumor tissues, demonstrating that both mRNA and protein levels of NUSAP1 were significantly upregulated in tumor tissues." (PMID 40535133, 2025). "NUSAP1, serving as a key regulator of the cell cycle, plays a pivotal role in tumor progression and alterations within the tumor microenvironment." (PMID 40535133, 2025). "Comparative analysis showed that NPC2 was upregulated in 11 tumor types, while NUSAP1 was upregulated in as many as 22 tumor types." (PMID 40393971, 2025). "Through mechanisms such as DNA repair, cell metabolism modulation, and cell cycle regulation, NUSAP1 facilitates tumor progression." (PMID 40535133, 2025). "This analysis revealed that patients with high NUSAP1 expression exhibited a lower proportion of immune and stromal cells but higher tumor cell purity compared to those with low NUSAP1 expression." (PMID 39781524, 2025). "Equal numbers of control and NUSAP1-silenced cells were subcutaneously injected into mice, and the control group exhibited faster tumor growth, resulting in larger tumor sizes and weights." (PMID 40393971, 2025). "The high-CMLHMS group exhibited upregulation of genes such as TRPC4AP, NUSAP1, EFNA1, KMT2A, and NCOA6, which are implicated in chromatin remodeling, cell proliferation, and tumor progression." (PMID 40144021, 2025). "NUSAP1 expression was significantly elevated in tumor tissues, correlating with poorer prognosis in LUAD patients." (PMID 39781524, 2025). "Remarkably, our experimental validations through qRT-PCR and IHC assays on clinical specimens corroborated the heightened expression of NUSAP1 in tumor tissues." (PMID 39781524, 2025). "NUSAP1 holds promise as a novel tumor biomarker, offering new avenues for clinical diagnosis and prognosis evaluation in digestive system cancers." (PMID 40535133, 2025). "Noteworthily, the entinostat-induced tumor growth inhibition was counteracted by NUSAP1 overexpression." (PMID 39430250, 2024). "The tumor growth rate and size were significantly decreased in the sh-NUSAP1 PANC-1 cell groups than in the NC group." (PMID 38229038, 2024). "TMA analysis revealed high expression of NUSAP1 in tumor tissues compared with normal tissues, and this upregulation was associated with a poor prognosis." (PMID 38229038, 2024). "In the recurrence of HCC, NUSAP1 can enhance tumor stemness by stimulating STAT3 nuclear translocation and RACK1 activation." (PMID 38441732, 2024).
tumor (continued). "An analysis of the clinical characteristics of PDAC revealed that high NUSAP1 expression was related to high tumor–node–metastasis (TNM) stage (χ2 = 8.971, P = 0.003)." (PMID 38229038, 2024). "Bioinformatics analysis revealed that APOC1, CFH, LGALS1 and NUSAP1 were highly expressed in bone metastases compared to primary tumours, whereas ADRB2, NR4A2 and ZNF331 exhibited the opposite trend (p < 0.05)." (PMID 39098992, 2024). "Previous research has demonstrated upregulation of NUSAP1 in HCC compared to non-tumor liver tissues, and that this upregulation promotes the proliferation and in vitro tumorigenicity of HCC cells." (PMID 38441732, 2024). "Using the GEPIA database, we found that NUSAP1 was highly expressed in tumor tissues compared with normal tissues (P < 0.05), and a high expression level of NUSAP1 was correlated with an unfavorable prognosis in PDAC patients (P = 0.0046)." (PMID 38229038, 2024). "NUSAP1 overexpression was found to significantly trigger tumor growth as evidenced by increased tumor volume and tumor weight, while entinostat generated the significant inhibitory effects." (PMID 39430250, 2024). "In vivo, LINC01393-knockdown decreased tumor growth and improved mice survival, while restoration of NUSAP1 partially reversed these effects." (PMID 36982952, 2023). "To explore potential therapeutic options that can counteract the tumor-promoting effects mediated by NUSAP1, we conducted CMap analysis." (PMID 37781040, 2023). "To further investigate the cell types express NUSAP1 in tumor tissues, we analyzed the single-cell expression of NUSAP1 using 79 datasets from the TISCH database." (PMID 37781040, 2023). "To further verify the function of NUSAP1 in tumor cell proliferation, we next conducted an in vivo experiment." (PMID 37781040, 2023). "Several studies have found that NUSAP1 is highly expressed in liver cancer, cervical cancer, breast cancer, and melanoma, which is closely related to tumor progression and metastasis." (PMID 36982952, 2023). "Subsequently, to further validate the impact of NUSAP1 expression on tumor prognosis, we utilized multiple GEO datasets." (PMID 37781040, 2023). "It is noteworthy that NUSAP1 appears to play diverse roles in tumor biology, exerting both pro- and anti-tumor effects, despite its high expression in all cancer tissues." (PMID 37781040, 2023). "To further investigate the functional role of NUSAP1 in tumor cells, we constructed NUSAP1 stably knockdown cells using A549 (LUAD) and MCF-7 (BRCA) cell lines." (PMID 37781040, 2023). "Further exploration and elucidation of the molecular mechanism of this difference will be crucial in designing tumor suppressing strategies targeting NUSAP1." (PMID 37781040, 2023). "In this study, we analyze NUSAP1 mRNA and protein expression levels in various human normal and tumor tissues, using data from TCGA, GTEx, CPTAC, HPA databases, and clinical samples." (PMID 37781040, 2023). "Further, the expression level of LINC01393, miR-128-3p, and NUSAP1 of orthotopically transplanted tumor were tested by qRT-PCR." (PMID 36982952, 2023). "Analysis of public databases and immunohistochemistry (IHC) results confirmed the high expression of NUSAP1 in tumor tissues across various cancer types." (PMID 37781040, 2023). "This elevated mRNA level was primarily attributed to the upregulation of two protein-encoding transcripts, indicating their potential as targets for NUSAP1 mRNA interference in tumor." (PMID 37781040, 2023). "Heatmap clustering results showed that the expression level of NUSAP1 was a predictive factor for prognosis in patients in the 25 tumor types, excluding BLCA, DLBC, ESCA, LAML, UCEC, and UCS." (PMID 37781040, 2023). "The reduced infiltration of CD4+T and NKT cells, which are key immune cells involved in tumor-killing, in high NUSAP1 tumors also contributes to an immunosuppressive tumor microenvironment 39-41." (PMID 37781040, 2023).
tumor (continued). "Our findings reveal that NUSAP1 is highly expressed in multiple tumor tissues across most cancer types and is primarily expressed in malignant and immune cells, according to single-cell sequencing data from the TISCH database." (PMID 37781040, 2023). "The downregulation of NUSAP1 and PCLAF after NCT is associated with the tumor response to chemotherapy and patient survival." (PMID 36478748, 2022). "By regression analysis, we determined that age (p < 0.008), tumor stage (p < 0.001), tumor mutation burden (TMB, p < 0.004), and NUSAP1 expression (p < 0.005) were different from PFS." (PMID 35710427, 2022). "To further inquire the expression of NUSAP1 and ZWINT in the (NAFLD)-associated HCC patients, we downloaded the data set GSE164441 including 10 paired NAFLD-associated HCC tumor and adjacent normal tissues." (PMID 35431924, 2022). "In PTC, NUSAP1 shows good diagnostic value and prognostic value; NUSAP1 impacts the cell cycle, immune-related pathways, and AITD and has a complex effect on the tumor microenvironment in PTC." (PMID 35710427, 2022). "In conclusion, NUSAP1 levels were elevated in BUC and were significantly associated with tumor diameter, pathological grade, pathological stage, and lymph node metastasis." (PMID 35487972, 2022). "Six genes were up-regulated in the tumor group and high-risk group consisting of SMAD3, CENPA, KIF23, NUSAP1, INCENP, and SMC4." (PMID 36401386, 2022). "Strong NUSAP1 staining was observed in specimens with large tumor diameter, high stage, high grade, and positive lymph node metastasis." (PMID 35487972, 2022). "The analysis of NUSAP1 and the tumor microenvironment lays the foundation, and the analysis results were consistent with expectations." (PMID 35710427, 2022). "By analyzing two results, we once again proved that NUSAP1 promoted tumor progression by regulating cell cycle." (PMID 34354737, 2021). "The function of NUSAP1 in tumor development need to be further explored by biomolecular and cellular research." (PMID 33784984, 2021). "The function of NUSAP1, the last signature of the prognostic model, has also been controversial in tumor progression." (PMID 33784984, 2021). "This implies that the genes were mainly expressed in the tumor cells, proving the clinical diagnostic value of CCNA2, CKAP2L, NCAPG, and NUSAP1 again." (PMID 33927744, 2021). "The high expression of NUSAP1 has been found in a variety of tumor types and is closely related to tumor cell proliferation, apoptosis, and drug resistance." (PMID 34322597, 2021). "NUSAP1 plays an oncogene role in tumors, which is mainly involved in regulating tumor cell proliferation and apoptosis." (PMID 34322597, 2021). "By analyzing two results, we once again demonstrated that NUSAP1 promoted tumor progression by regulating cell cycle." (PMID 34354737, 2021). "The logistic regression revealed that low NUSAP1 expression in CESC was related to advanced tumor stage in TCGA database." (PMID 32226503, 2020). "In order to further confirm the biological functions of NUSAP1, we established a xenograft tumor model by inoculating BGC823 cells that expressed scramble shRNA or NUSAP1 shRNA into NOD/SCID mice and monitored tumor size for 28 days." (PMID 33489890, 2020). "We further examined NUSAP1 in a pair of peritumoral and tumor tissues, and NUSAP1 was upregulated in the tumor tissue." (PMID 32317623, 2020). "In line with the tumor growth curve, NUSAP1 knockdown resulted in a marked reduction in tumor mass and weight." (PMID 33489890, 2020). "Different from other reports, we have not identified the correlation between NUSAP1 expression and tumor size, but our study first proposes that NUSAP1 functions as a prognostic factor for overall survival in patients with GC." (PMID 33489890, 2020). "This study indicates that NUSAP1 acts as a tumor-related gene in GBM, and that NUSAP1 inhibits cell proliferation and induces apoptosis and DNA damage in GBM." (PMID 32317623, 2020).
tumor (continued). "An abnormal cell cycle is an important feature of tumor formation, and currently, the role of NUSAP1 in cancer is being actively investigated." (PMID 32420375, 2020). "The tumor sphere formation obtained from NUSAP1-silenced cells generated approximately 3-fold fewer spheres compared with control cells." (PMID 30678687, 2019). "Meanwhile, we found that the lymph nodes in tumours formed from NUSAP1-transducted cells displayed higher numbers of luciferase-positive tumour cells than tumours formed vector-control cells." (PMID 30678687, 2019). "In the present study, we reported that NUSAP1 significantly enhanced tumor sphere formation and the expression levels of several stem cell-related genes in vitro, and promoted metastasis in vivo." (PMID 30678687, 2019). "As expected, we found that NUSAP1 upregulation promoted tumor sphere formation of SiHa and HeLa cells, generating nearly 3-fold more spheres compared with control cells." (PMID 30678687, 2019). "Conversely, the lymph node formed from NUSAP1-silenced cells had less luciferase-positive tumour cells than vector-control tumours." (PMID 30678687, 2019). "Recently, the important roles of NUSAP1 in tumorigenesis have been revealed in several types of tumor." (PMID 30678687, 2019). "NUSAP1 knockout resulted in reduced migration in PCa cell lines, reduced tumor volume in PCa xenografts, and a NUSAP1 knockdown gene expression signature correlated with better outcome in patient PCa samples." (PMID 29545934, 2018). "The gene expression patterns elicited by NUSAP1 overexpression or knockdown fall into a remarkably consistent set of pathways related to tumor progression." (PMID 28404898, 2017). "Our data suggests a direct functional role of NUSAP1 in tumor progression, bolstering its role as a prognostic biomarker and warranting further investigation into its function and therapeutic potential." (PMID 28404898, 2017). "The findings also consistently showed that the tumor margins of the NUSAP1-overexpressing tumor samples were more incomplete, while the tumor margins of NUSAP1-suppressed tumor specimens were more complete." (PMID 28899410, 2017). "Knockdown of NUSAP1 expression produced a significant reduction in tumor size measured by bioluminescence and calipers." (PMID 28404898, 2017). "Tumor weights were also lower when NUSAP1 had been knocked down, consistent with decreased tumor volume and reduced proliferation." (PMID 28404898, 2017). "For all tissue sites combined, the percentage of mice with metastases was significantly higher when NUSAP1 was overexpressed in the primary tumor compared to EGFP overexpression." (PMID 28404898, 2017). "The data suggest that overexpressed NUSAP1 induces dysregulated cell cycle leading to the active proliferation of tumor cells." (PMID 26554377, 2015). "Further experimental and clinical investigations are warranted to elucidate the precise role of NUSAP1 in tumor biology, which may provide novel insights for the treatment of malignant tumors, particularly those of the digestive system." (PMID 40535133, 2025). "By suppressing NUSAP1 expression, more precise tumor control may be achieved in the context of personalized therapy, offering better outcomes for patients." (PMID 39975552, 2025). "As a targetable molecule, NUSAP1 could influence key immune regulatory pathways and modulate the tumor’s response to immunotherapy." (PMID 39975552, 2025). "Therefore, an in-depth exploration of the interaction mechanisms between NUSAP1 and these signaling pathways will contribute to the formulation of innovative anti-tumor therapeutic approaches." (PMID 40535133, 2025). "NUSAP1 exerts a potential influence on modulating the tumor immune microenvironment in HCC." (PMID 40535133, 2025).